IL11 (interleukin 11)
Diseases named in the same sentence as IL11 in open-access papers (continued):
Sharing a sentence is not in itself a finding about the gene and the disease.
infertile (15 papers, 2004 to 2025). "IL-11Ra deficiency leads to infertility due to impaired decidualization; IL-11 expression increases significantly during the late secretory phase and early pregnancy." (PMID 39794729, 2025). "Female mice with a null mutation in the gene encoding interleukin-11 receptor α (IL-11Rα) are infertile due to disrupted decidualization, suggesting a critical role for IL-11 and its target genes in the decidual response." (PMID 15537430, 2004). "Female interleukin-11 receptor α (IL-11Rα) deficient mice are infertile due to disrupted decidualization, suggesting a critical role for IL-11 and its target genes in implantation." (PMID 15537430, 2004). "However in our study, the increased expression of PDIA3 during receptive phase/mid-secretory phase endometrium of infertile women might induce IL-11/STAT3 signalling pathway, which in turn cause proliferation and growth of endometrial cells." (PMID 25405865, 2014). "In addition, in some women with endometriosis associated infertility, IL-11 and LIF immunoreactivity are reduced in glandular epithelium suggesting that both cytokines may also contribute to the pathology of infertility of unknown cause." (PMID 18047677, 2007). "Mice with IL-11 gene knockout or those treated with an IL-11 antagonist display infertility characterized by impaired stromal cell differentiation and implantation failure." (PMID 39794729, 2025). "PBMCs from infertile women with ASA produce less IL-11 early upon stimulation with sperm cells as compared to healthy women." (PMID 22952917, 2012). "IL-11 immunoreactivity was moderate to high in glandular epithelial cells from all control fertile women and some infertile women." (PMID 18047677, 2007). "Minimal staining for IL-11 was observed in the stromal compartment in tissues from fertile and infertile women." (PMID 18047677, 2007). "We observed a significant decrease in IL-11 and pSTAT3 in uterine glandular epithelium in some women with infertility compared to normal cycling fertile women." (PMID 18047677, 2007). "In contrast to the present study IL-11, IL-11Rα and LIF staining were decreased in glandular epithelial cells in women with endometriosis associated infertility." (PMID 18047677, 2007). "This is the first demonstration of reduced endometrial pSTAT3 and IL-11 in some women with unexplained infertility." (PMID 18047677, 2007). "Female mice with impaired IL-11 signaling are infertile due to decidualization defects." (PMID 39443665, 2024). "However, mean IL-11 staining in glandular epithelium was consistently more intense in tissues from control women compared to the infertile women (1.7 ± 0.2 vs 1.1 ± 0.2 respectively, P < 0.05), although there was a clear overlap between the groups." (PMID 18047677, 2007). "Although the function of IL-11 and pSTAT3 in endometrial glands needs to be elucidated, unexplained infertility in some women may be due to reduced levels of either IL-11 or pSTAT3." (PMID 18047677, 2007). "Understanding the mechanisms of IL-11 and pSTAT3 action in endometrial epithelium may provide new therapeutic strategies for unexplained infertility." (PMID 18047677, 2007). "Endometrial protein abundance for IL-11, pSTAT3, IL-11Rα and LIF was compared in women with primary unexplained infertility and normal fertile women." (PMID 18047677, 2007). "Reduced IL-11 production and STAT3 phosphorylation may contribute to unexplained infertility in some women." (PMID 18047677, 2007). "It is also plausible that IL-11 and LIF stimulate pSTAT3 in glandular epithelium but the levels of STAT3 protein may be low in glandular epithelium of some infertile women." (PMID 18047677, 2007).
infertile (continued). "Unexplained infertility is likely caused by several defects therefore it is not surprising that we identified cohorts of infertile women with defective IL-11 and pSTAT3 production." (PMID 18047677, 2007). "We hypothesized that IL-11, IL-11Rα, LIF and pSTAT3 are dysregulated in endometrium from women with unexplained infertility during the 'window of implantation'." (PMID 18047677, 2007). "Seven out of the ten women with infertility had very low levels of both IL-11 and pSTAT3 protein in the glandular epithelium (data no shown)." (PMID 18047677, 2007). "There are very few studies examining the role of IL-11 and no studies for pSTAT3 in infertility in women." (PMID 18047677, 2007). "Likewise, the loss of classic IL-11 signaling is associated with defects in embryo implantation; however, the inhibition of IL-11 trans-signaling in mice does not result in infertility." (PMID 32765502, 2020). "Also, the mechanism of control over the rate of gene transcription or transcriptional regulation is altered in genes involved in chronic endometritis and the inflammatory response (IL-11, CCL4), growth factors (IGFBP1), and apoptotic proteins (BCL2, BAX, CASP8) in infertile patients." (PMID 33329514, 2020). "Interestingly, glandular epithelium from women with infertility that had low IL-11 staining did not consistently have low pSTAT3 staining." (PMID 18047677, 2007). "IL-11, pSTAT3, IL-11Rα and LIF staining was overall low and patchy or absent in luminal epithelium of both infertile and fertile women." (PMID 18047677, 2007).
gastric tumors (14 papers, 2010 to 2024). "Since inflammatory cytokines, i.e. Il-1β, Il-6 and Il-11 have been associated with development of gastric tumors, we analyzed the hyperplastic antra of Gast−/− mice for the proinflammatory cytokines." (PMID 23110168, 2012). "Gastric tumors in gp130FF mice, which harbor a knock in germline mutation in the shared IL-6/IL-11 receptor subunit gp130, arise from excessive IL-6/IL-11 dependent STAT3 activity; these tumors remain associated with chronic inflammation and immune cell infiltration." (PMID 31227713, 2019). "Gastric tumors in the Gp130FF model are driven by IL-11 signalling, which we have documented previously through genetic ablation of the ligand-binding IL-11RA receptor subunit, or following therapeutic administration of the IL-11 antagonist IL-11-mutein." (PMID 37957015, 2024). "Collectively, these data indicate that tumor-derived IL-11 induces Il33 gene expression in gastric tumor cells, which triggers the secretion as well as the de novo synthesis of cytokines and chemokines by mast cells to produce a tumorigenic immune environment." (PMID 31227713, 2019). "Here, we provide evidence for IL-33 expression in gastric tumor epithelium to also be stimulated by an IL-11/Stat3 signaling cascade, which we and others have identified as an absolute requirement for effective growth of gastrointestinal tumors." (PMID 31227713, 2019). "IL-11 has been shown to promote gastric tumor development, while, conversely, deletion of the IL-11 coreceptor alpha ablated the development of gastric tumors." (PMID 26543325, 2015). "IL-11 expression is increased in multiple mouse models of progressive gastric pathology, and in human gastric tumors." (PMID 25528766, 2015). "gp130757FF mice develop distal stomach tumours characterised by elevated gastric IL-11 driven STAT3 activation." (PMID 24804649, 2014). "Our current data are consistent with these outcomes, in that WP1066 shows a strong trend to inhibit Reg1 in gastric tumours of the gp130757FF mouse along with IL-6 and IL-11 inhibition." (PMID 24804649, 2014). "In addition, we observed IL-11, but not IL-6 levels, were significantly reduced in Gp130FF; Yap1KO derived tumor lysates, consistent with our previous observation that IL-11 is a key player in gastric tumor development." (PMID 37957015, 2024). "This includes three consensus TTC(N3)GAA Stat3 binding sites, which we confirm here by the ChIP analysis of DNA isolated from gastric tumors from Gp130F/F mice stimulated with IL-11 and comprising the two functionally validated proximal sites at positions 86,400,807 and 86,400,717 in melanoma cells." (PMID 35053428, 2022). "Furthermore, expression of mRNA transcripts for the bona fide STAT3‐target genes Socs3, Icam1, and Reg3a, which are both induced by IL11 in gastric tumors, were significantly decreased in tumors from bazedoxifene‐treated animals." (PMID 30885958, 2019). "Additionally, we conducted a chromatin immunoprecipitation (ChIP) experiment on DNA from gastric tumors of gp130FF mice 60 min after acute systemic administration of IL-11." (PMID 31227713, 2019). "Gastric tumor formed in gp130Y757F/Y757F mice could be significantly abrogated by IL-11Rα knock-out and also by IL-11 signaling antagonist." (PMID 25929737, 2015). "However, therapeutic application of Stat3-antisense oligonucleotides or IL11 antagonists to gp130Y757F mice, suggest that growth and maintenance of gastric tumours remains dependent on the continuous activation of Stat3." (PMID 20478049, 2010). "Up-regulation of YAP1, IL11, IL6, and STAT3 mRNA transcript expression was observed in human gastric tumor samples when compared with normal gastric tissue." (PMID 37957015, 2024). "Bazedoxifene administration reduced gastric tumor burden in gp130Y757F mice, where tumors arise exclusively through excessive gp130/STAT3 signaling in response to the IL6 family cytokine IL11." (PMID 30885958, 2019).
gastric tumors (continued). "Gastric tumours from WP1066- treated mice had reduced polymorphonuclear inflammation, coincident with inhibition of numerous proinflammatory cytokines including IL-11, IL-6 and IL-1β, as well as the growth factors Reg1 and amphiregulin." (PMID 24804649, 2014). "Bazedoxifene suppresses gastric tumor growth in gp130Y757F mice irrespective of their gender, in which tumors arise through excessive IL11‐dependent STAT3 signaling." (PMID 30885958, 2019). "We have identified a prominent role for non-haematopoietic IL11 rather than (myeloid-derived) IL6 in promoting gastric tumour formation in the gp130Y757F mouse model." (PMID 20478049, 2010). "Since the gastric tumors that form in gp130Y757F mice are exquisitely sensitive to the inhibition of IL-11 signaling, we systemically treated age-matched mice with an anti-IL-11R monoclonal antibody (CSL-4E5) or IL-11 Mutein-PEG (a recombinant protein that is a potent IL-11 signaling antagonist)." (PMID 38542101, 2024).
idiopathic pulmonary fibrosis (14 papers, 2019 to 2025). Idiopathic pulmonary fibrosis (IPF) is a nonneoplastic pulmonary disease that is characterized by the formation of scar tissue within the lungs in the absence of any known cause. "This suggests that IL-11 is a therapeutic target of idiopathic pulmonary fibrosis (IPF)." (PMID 34070895, 2021). "IL-11 plays an important role in idiopathic pulmonary fibrosis (IPF), which can differentiate fibroblasts into collagen-secreting, actin alpha 2 and smooth muscle-positive (ACTA2+) myofibroblasts." (PMID 39199292, 2024). "IL-11 was also shown to be mitogenic for lung fibroblasts isolated from either healthy donors or those with idiopathic pulmonary fibrosis (IPF)." (PMID 31156640, 2019).
lung adenocarcinoma (14 papers, 2016 to 2025). A carcinoma that arises from the lung and is characterized by the presence of malignant glandular epithelial cells. "IL‐11 drives tumour progression and is linked to poor survival in lung adenocarcinoma patients, as well as an immunosuppressive tumour microenvironment." (PMID 40673604, 2025). "IL‐11 has been shown to be upregulated by cancer cells and cancer‐associated fibroblasts in lung adenocarcinoma, leading to cancer progression." (PMID 38023717, 2023). "Moreover, IL‐11 has been shown to be upregulated by cancer‐associated fibroblasts in lung adenocarcinoma after treatment with chemotherapy as a chemoresistance mechanism." (PMID 38023717, 2023). "To study the role of IL‐11 as a prognostic biomarker, we examined two cohorts of patients with early‐stage lung adenocarcinoma." (PMID 40673604, 2025). "The cytokine interleukin (IL)‐11 has been shown to play a role in promoting fibrosis and cancer, including lung adenocarcinoma, garnering interest as an attractive target for therapeutic intervention." (PMID 38023717, 2023). "We show that blocking IL‐11 with an engineered high‐affinity decoy ligand, enIL‐11, inhibits cell signaling and proliferation, and delays tumor progression in a mouse model of lung adenocarcinoma." (PMID 38023717, 2023). "IL11 signaling in NSCLC has been investigated mostly in the A549 cell line as a model for lung adenocarcinoma (LUAD), the most common subtype of NSCLC." (PMID 35883698, 2022). "The anti-apoptotic effects of IL-11 can be prevented by suppressing STAT3 phosphorylation or silencing IL-11Rα expression in lung adenocarcinoma." (PMID 34503172, 2021). "Cisplatin treatment increases Interleukin-11 (IL-11) levels in CAFs which protects lung adenocarcinoma cells from apoptosis." (PMID 34503172, 2021). "Another study reported that IL-11 secreted by cisplatin-treated CAFs played a vital role in chemoresistance of lung adenocarcinoma patients." (PMID 29988148, 2018). "For example, increased secretion of IL-11 from CAFs treated with cisplatin mediates lung adenocarcinoma cell chemoresistance through paracrine signalling of the IL-11/IL-11R/STAT3 pathway." (PMID 29176691, 2017). "In conclusion, chemotherapy-induced IL-11 upregulation in CAF promotes lung adenocarcinoma cell chemoresistance by activating IL-11R/STAT3 anti-apoptotic signaling pathway." (PMID 27922075, 2016). "To further test the effect of IL-11 on lung adenocarcinoma cells, we added recombinant human interleukin-11(rhIL-11) with different concentration to the culture medium of A549 and H1975 cells." (PMID 27922075, 2016). "IL-11, a member of the IL-6 family, is upregulated in cisplatin-stimulated cancer-associated fibroblasts, and then IL-11 activates the STAT3 signaling pathway, leading to lung adenocarcinoma cell resistance to cisplatin." (PMID 32872659, 2020). "As confirmed in lung adenocarcinoma cells in vivo and in vitro, IL-11 could protect cancer cells from cisplatin-induced apoptosis and thus promote their chemoresistance." (PMID 27922075, 2016). "The enhancement of STAT3 phosphorylation via IL-11 was also observed in lung adenocarcinoma cells." (PMID 27922075, 2016). "Therefore, the promoting role of IL-11 on chemoresistance of lung adenocarcinoma prompts us to reassess the use of this cytokine in cancer therapy." (PMID 27922075, 2016). "In the present study, the phosphorylation inhibitor of STAT3 could inhibit the effect of IL-11 on promoting the colony formation and reducing apoptosis rate (early and later) of lung adenocarcinoma cells." (PMID 27922075, 2016). "In the study, colony formation and anti-apoptosis experiments showed that IL-11 could enhance anti-apoptosis ability and facilitate colony formation of lung adenocarcinoma cells treated with cisplatin." (PMID 27922075, 2016).
lung adenocarcinoma (continued). "Taken together, our results showed that activation of IL-11/IL-11R/STAT3 anti-apoptotic signaling could augment lung adenocarcinoma cells resistance to cisplatin-induced apoptosis by upregulating Bcl-2 and Survivin." (PMID 27922075, 2016). "The upregulation of Bcl-2 and Survivin were induced by IL-11 in the lung adenocarcinoma cell." (PMID 27922075, 2016). "Additionally, IL‐11 has been identified as a therapeutic target for lung adenocarcinoma." (PMID 38023717, 2023). "To better elucidate the mechanisms of chemoresistance induced by IL-11, we found that IL-11 could attenuate cisplatin-induced apoptosis rate of lung adenocarcinoma cells accompanied with the activation of anti-apoptotic STAT3 signaling including Bcl-2 and Survivin overexpression." (PMID 27922075, 2016). "It has previously been reported that IL‐11 promotes tumour progression and EMT in lung adenocarcinoma through the activation of the STAT3/HIF‐1α/EMT signalling pathways." (PMID 40673604, 2025).
Sepsis (14 papers, 2008 to 2025). Sepsis is defined as life-threatening organ dysfunction caused by a dysregulated host response to infection. "In the regulation of cytokine production, some cytokines had been proved to be beneficial for the control of sepsis, such as the anti-inflammatory cytokines of IL-1Ra, IL-4, IL-6, IL-10, IL-11, IL-13, IL-35, and TGF-β." (PMID 34938184, 2021). "Different from other IL-6 family cytokines, IL-11 holds anti-inflammatory function against chronic inflammatory diseases, lipopolysaccharide-induced sepsis, etc." (PMID 25946003, 2015). "Different from other IL-6 family members, IL-11 administration reduces inflammatory responses in chronic inflammatory diseases, lipopolysaccharide-induced sepsis, macrophages inflammation, nephrotoxic nephritis and T-cell mediated liver injury." (PMID 25946003, 2015). "As anti-inflammatory cytokines can also play a role in the response to severe sepsis we next looked at the levels of IL-10, IL-4, IL-11 and IL-5." (PMID 21124895, 2010). "Interleukin-11 (IL-11), a cytokine interacting with hematopoietic and non-hematopoietic cells, has demonstrated therapeutic potential in systemic inflammatory conditions including sepsis." (PMID 40003683, 2025). "In mice, IL-11 reduces the inflammatory responses to LPS-induced sepsis." (PMID 37942584, 2023). "The LPS induced il11 gene expression may reflect a cell protective mechanism in sepsis." (PMID 19087328, 2008). "Further research was conducted to reveal the associations between m6A patterns and inflammatory factors, including interleukin (IL)-1β, IL-8, IL-10, IL-11 and TNF receptor superfamily member 1A (TNFRSF1A), in sepsis." (PMID 36781867, 2023). "Studies analyzing proinflammatory cytokines, such as IL-8, IL-12, IL-17A, and IL-18, and anti-inflammatory cytokines, such as IL-4, IL-10, and IL-11, have reported no effective neutralizing antibodies to improve the outcomes of human sepsis." (PMID 40136690, 2025).
pancreatic cancer (13 papers, 2016 to 2025). "Elevated levels of IL-11 are found in several other types of cancer, including pancreatic cancer, skin cancer, and bone cancer, although a precise role for IL-11 signaling in many of these cancers remains to be defined." (PMID 32765502, 2020). "The human pancreatic carcinoma cells decreased serum induce-IL-11 in response to Fra-1 blocking siRNA even after making use of Ras activator.Both Fra-1 and IL-11 are relatively overexpressed in oxidative stress condition." (PMID 29914371, 2018). "Moreover, pancreatic cancer cells secrete IL‐11 and CCL20 in response to NTS stimulation, which in turn evoke inflammatory responses in the tumor microenvironments." (PMID 33034134, 2021). "Furthermore, IL-6 showed a stronger ability to activate/phosphorylate STAT3 at Tyr705 than did LIF or another IL-6 family member, IL-11, in human pancreatic cancer cells." (PMID 31296870, 2019). "These genes, AREG, CXCR4, IL11, KITLG and OSCAR, are known to play a significant role in tumour progression and metastasis promotion of prostate cancer as well as colorectal or pancreatic cancers." (PMID 39374163, 2025). "It is found that STAT3 forms a positive loop with two inflammatory cytokines IL-6 and IL-11 in pancreatic cancer: STAT3 directly affects the expression of IL-6 and IL-11, both of which are STAT3 activating cytokines." (PMID 26887043, 2016).